IL10 (interleukin 10)
Diseases named in the same sentence as IL10 in open-access papers (continued):
Sharing a sentence is not in itself a finding about the gene and the disease.
dengue (continued). "Therefore, it appears that IL-10 only had an effect on DENV specific immune responses in acute dengue viral infection and did not appear to have any effect on existing memory T cell responses to non dengue viral peptides." (PMID 24040431, 2013). "However, serum IL-10 had a poor discriminatory value in identifying those with severe dengue and non severe dengue and therefore, is unlikely to be useful as a robust biomarker in this population." (PMID 23883139, 2013). "However, serum IL-10 was higher in patients with severe secondary dengue infection (mean 329.1, SD ± 647.1 pg/ml) when compared to those with non severe dengue (mean 164, SD ± 155.1 pg/ml) (data not shown)." (PMID 23883139, 2013). "Interleukin-10 showed a decreasing trend in patients without warning signs, however remained high in DwWS patients throughout the disease in concordance with several studies that have suggested IL-10 in dengue pathogenesis." (PMID 23284941, 2012). "IFN-γ, IL-10 and IL-18 have been frequently reported to be higher in the serum of DHF/DSS patients compared to DF patients and may thus be considered as immune markers of severe dengue in humans." (PMID 31009499, 2019). "Many studies have investigated the cytokines patterns in serum samples in patients with DHF and these studies have shown that TNFα, IL-6, IL-10, IL-1β, IFN-γ, IL-4, IL-13, IL-7, GM-CSF, MIF, along with several other cytokines were elevated in patients with DHF when compared to dengue fever (DF)." (PMID 23209731, 2012). "Although, there are some studies showing that IL-6, IL-10 and TNF-α are related to dengue, the roles of IL-37b in dengue fever have not been established." (PMID 37024713, 2023). "When stimulated with TLR9 agonist CpG, we have shown that activation markers CD69 and CD86 were not up-regulated and that no secretion of IL-10 and TNF-α was observed in B cells from dengue patients compared to healthy donors." (PMID 34293057, 2021). "Four eligible biomarkers, CRP, TNF-α, IL-10, and IFN-γ, found no significant variation in marker levels when comparing severe and non-severe dengue." (PMID 34610027, 2021). "Among the host inflammatory biomarkers, GM-CSF, IFN-γ, IL-10, IL-15, IL-8, MCP-1, IL-6, MIP-1β, and TNF-α levels were significantly increased in dengue with and without warning signs, in severe dengue patients in comparison to healthy controls." (PMID 30626045, 2019). "The percentages of transitional (CD24hiCD38hi cells), which include regulatory, IL-10-producing B cells (Breg), within CD19+ B cells, were not different in dengue patients compared to patients with DENV-negative febrile controls." (PMID 31736948, 2019). "In summary, we found that patients with severe dengue had lower T cell numbers but that DV-NS3 specific T cells produced high levels of IFNγ but not IL-3, IL-13, IL-2, IL-10 or IL-17." (PMID 23209731, 2012). "We found that whilst patients with severe dengue had lower total T cell numbers, the DV-NS3 specific T cells persisted and produced high levels of IFNγ but not TNFα, IL-3, IL-13, IL-2, IL-10 or IL-17." (PMID 23209731, 2012). "IL-10 blockade significantly increased IFNγ production, and other antiviral responses such as CD107a expression and TNFα production in response to DENV-NS3 peptides but not to non dengue viral proteins in acute dengue infection." (PMID 24040431, 2013). "Taken together, we hypothesize that the IL-10 elevation in these samples indicates it plays a role in DENV replication, and elevation during DF can be attributed to serotype-specific structural/non-structural dengue proteins and/or homotypic infection, which warrant further research." (PMID 34447698, 2021).
leishmaniasis (114 papers, 2005 to 2026). Infectious disease that is transmitted through the bite of hematophagous female phlebotomine sand flies. "In the context of leishmaniasis, these immunosuppressive cells have been tightly linked to Leishmania survival through the production of IL-10 and TGF-β, while simultaneously inhibiting ROS production." (PMID 40142422, 2025). "This immunomodulation is vital to avoid relapses of leishmaniasis, which are associated with an increased Th2 response and higher IL-10 production." (PMID 39194287, 2024). "This is noteworthy, as higher amounts of IgG in leishmaniasis have been associated with susceptibility, as IgG induces the production of regulatory IL-10 in monocytes, contributing to the inhibition of cellular responses in chronic DCL patients." (PMID 38359037, 2024). "Under this study, 3 cytokines (IL-4, IL-6 and IL-10), with a role in increasing susceptibility towards leishmaniasis progression (Th2 response), were estimated in PBMC supernatants." (PMID 38918456, 2024). "We also evaluated IL-10; a cytokine that has been involved in both susceptibility to leishmaniasis and the regulation of CL development." (PMID 38064516, 2023). "Susceptibility to leishmaniasis has been extensively associated with anti-inflammatory cytokines, as demonstrated in IL-4, IL-6, IL-10 and IL-13 deficient BALB/c mice." (PMID 37691941, 2023). "Genetic IL-10 deficiency as well as transient blockade of IL-10 signaling via anti-IL-10 receptor antibodies resulted in sterile cure of Leishmaniasis major, pointing towards a potential therapeutic mechanism." (PMID 36370291, 2023). "Previous studies have shown that specific polymorphisms are associated with the regulatory role of IL-10 and disease progression several IL-10 polymorphisms have been investigated regarding their roles in leishmaniasis, but the results are inconsistent." (PMID 35778471, 2022). "Interleukin 10 (IL-10) is associated with the progression of leishmaniasis because it inhibits the leishmanicidal action of macrophages and the production of mediators such as IFN-γ and nitric oxide." (PMID 35778471, 2022). "The rcasIL-10R1 produced in this baculovirus-insect cell system demonstrated the blockade of the IL-10 signaling pathway and the restoration of in vitro lymphoproliferative response in dogs with leishmaniasis caused by L. infantum." (PMID 33465107, 2021). "An association has been reported between IL-10, a suppressive cytokinegene expressed by Treg cells, and leishmaniasis." (PMID 32347041, 2021). "The production of cytokines, such as IL-4, IFN-γ, and IL-10, plays a key role in the susceptibility or resistance to leishmaniasis." (PMID 32867857, 2020). "Th2 cells contribute to susceptibility of BALB/c mice to leishmaniasis by producing cytokines (such as IL-4 and IL-10) that deactivate infected macrophages and suppress the iNOS pathway, which is important for eliminating intracellular Leishmania parasites." (PMID 32784615, 2020). "In Leishmaniasis, the inhibition of IL-12 along with an induction of IL-10 and TGFβ underlies the bias towards a Th2 response." (PMID 30679687, 2019). "Further, IL-10 plays a substantial role in the pathogenesis of leishmaniasis by causing the downregulation of Th1 response, MΦ activation and antigen presentation by DCs." (PMID 31024534, 2019). "The production of cytokines in leishmaniasis plays a key role in maintaining susceptibility or resistance to disease, with cytokines IL-10, IL-4, TGF-β and IFN-γ being more relevant." (PMID 28848541, 2017). "Treatment caused a significant decrease in IL-10 (21.33 ± 3.66 pg/ml, p<0.01), reiterating its importance in leishmaniasis." (PMID 26496711, 2015). "In human leishmaniasis, elevated intra-lesional FoxP3 and IL-10 were associated with unresponsiveness to treatment during L. amazonensis infection." (PMID 26465878, 2015). "IL-10 is repeatedly implicated as an immunosuppressive factor in both human and experimental leishmaniasis." (PMID 21655313, 2011).
leishmaniasis (continued). "Finally, serum levels of IFN-γ, TNF, CCL2, IL-12p70, IL-6, and IL-10 mediator previously implicated in the progression of leishmaniasis were measured using flow cytometry with the Mouse Inflammation CBA kit." (PMID 41259559, 2025). "We performed a systematic review and meta-analysis to determine whether single nucleotide polymorphisms (SNPs) of IL-10 influence the progression of leishmaniasis." (PMID 35778471, 2022). "In addition, rcasIL-10R1 was able to bind to homologous IL-10 and block IL-10 signaling pathway, as well as to promote lymphoproliferation in dogs with leishmaniasis caused by L. infantum." (PMID 33465107, 2021). "The IL-10 cytokine in the spleen seems to be an indicator of leishmaniasis susceptibility, and its reduction observed in the CanL group after supplementation with ATRA, 1,25(OH)2VD3, and SZn may favor the regulation of immunity." (PMID 34573521, 2021). "In addition, rcasIL-10R1 was evaluated in vitro with respect to its binding ability and blocking of the homologous IL-10 signaling pathway, as well as promoting lymphoproliferation in dogs with leishmaniasis caused by L. infantum." (PMID 33465107, 2021). "However, in leishmaniasis, healing is predominantly associated with diminished expression of IL-10 mRNA." (PMID 31024534, 2019). "In addition, leishmaniasis pathogenesis is associated with the blockage of a Th1 response development, leading to a greater number of IL-4 and IL-10-producing cells in the lesions." (PMID 31024859, 2019). "Nonetheless, IL-10 impairs cure of acute leishmaniasis, illustrated in IL-10 deficient mice infected with L. (L.) amazonensis or L. (L.) mexicana which are still unable to eliminate infection despite strong IFNγ production, at least in part through the action of IL-4." (PMID 28629171, 2017). "It is well characterized that IL-10 plays an important role in susceptibility to leishmaniasis." (PMID 25933287, 2015). "In addition, our findings related to the LieIF2 and LieIF2B production of IL-10 in mice infected with L. major also highlight the role of these factors as cellular markers of the disease and link them with the promotion of susceptibility against leishmaniasis." (PMID 29675401, 2018). "Thus, the role of IL-17 in both leishmaniasis forms (cutaneous and visceral) may be strictly associated with neutrophil function, infection stage, and antioxidant capacity, as well as IL-10 regulation." (PMID 29163510, 2017). "The redirection of the immune response elicited against the LiPABP family (from IL-10 towards IFN-γ mediated responses) by genetic vaccination was able to induce a partial protection against the development of the disease in a highly susceptible murine model of leishmaniasis." (PMID 25955652, 2015). "Nevertheless, the role played by IL-10 in either activating or suppressing NK cell activity in leishmaniasis remains undefined." (PMID 39963187, 2025). "PEPCK335–351 was used as a control in the analysis of IFN-γ/IL-10 ratio, because it activates strong Th1 immune responses and provides significant protection against leishmaniasis." (PMID 40134009, 2025). "Our data suggests a similar imbalance between cytotoxic and regulatory responses, with reduced IL-10+ T cells and increased IL-17+ T cells potentially contributing to severity, as IL-10 limits Th17-mediated pathology in experimental leishmaniasis." (PMID 40831564, 2025). "Our data for the regulatory cytokine IL-10 indicated higher than control levels produced in response to the ΔCpB antigen in all patients cured of leishmaniasis." (PMID 41272851, 2025). "In human leishmaniasis, IL-10 plays a central role in the course of the immune response in VL, contributing to the chronicity of the disease through suppression of host immunity and effector T-cell functions." (PMID 38469319, 2024).
leishmaniasis (continued). "In this study, two undernutrition infected groups showed more severe leishmaniasis, with increased parasite load in the spleen, upregulated expression of PD-1 and PD-L1, elevated serum IL-4 and IL-10, and decreased serum antibodies, TC and LDL-C." (PMID 38185681, 2024). "Further, the expression of key cytokines involved in leishmaniasis-mediated inflammation, including IL-1β, IL-10, IL-12 and TNF-α, remained constant across all experimental groups." (PMID 39076982, 2024). "Test for a possible regulatory role of miR-194 in the production of cytokines IL-1β, IL-6, IL-4, TNF-α, IFN-y, TGF-β, and IL-10, PBMCs from healthy dogs and those with leishmaniasis were transfected with miR-194 Mimic and Inhibitor." (PMID 38241360, 2024). "Similar to Schistosoma japonicum, the level of IL-10 have a direct impact on protective immunity in Leishmaniasis major and Leishmaniasis tropica infection models." (PMID 36370291, 2023). "Still, our data demonstrated an overall increased expression of inflammasome-related genes such as Gsdmd, Nlrp3, Casp1, Casp4, Il1b, Ifng, Tnfa, Il10, and Il17a when we compared Leishmaniasis patients with controls." (PMID 36828815, 2023). "To conclude we posit that computational modeling of IL12 and IL10 reciprocity through NFAT5 in Leishmaniasis helps us to understand the signaling mechanism responsible for parasite survival." (PMID 35126456, 2021). "In leishmaniasis, IL-10 (as a potent immunosuppressive cytokine) is vital for the persistence of the parasite and can exacerbate the disease." (PMID 34140933, 2021). "In leishmaniasis, IL-10 secreted by CD5+CD1d+ B cells polarized the Th cell response toward the Th2 phenotype, leading to susceptibility to infection with the parasite in BALB/c mice." (PMID 33750870, 2021). "As well, inhibition of IL-10, a cytokine that is known to contribute to disease progression in leishmaniasis, has been reported to be beneficial in studies conducted in mouse models and patients with visceral leishmaniasis." (PMID 32784615, 2020). "Previously, it has been reported that stimulation with IL-12 or blocking IL-10 signaling, result in restoration of specific lymphoproliferative response in dogs with leishmaniasis." (PMID 31961868, 2020). "It is well known that pro-inflammatory (e.g., IFN-γ, TNF-α, IL-1, IL-12) and anti-inflammatory (e.g., IL-4, IL-10, TGF-β) cytokines play different roles in resistance/susceptibility and the immunopathogenesis of leishmaniasis." (PMID 33114674, 2020). "IL-27 induces CD4+ T cell-derived IL-10, which is canonical disease-enhancer in leishmaniasis, whilst at the same time it suppresses Th17/IL-17, both of which can promote disease progression when present." (PMID 33415318, 2020). "Both the IL-10 and IL-6 response is triggered which upregulates in all forms of leishmaniasis and their level subsides as the patients recover from the disease." (PMID 32555598, 2020). "In the current study, the significant reduction in IL-10 production in boththe spleen and lymph node of the AD-MSCs treated group demonstrated the efficacy of MSCs inthe treatment of leishmaniasis." (PMID 32779429, 2020). "Rather than an inert Th1 type response, a Th2 / Th1 type response associated with the production of down-regulating cytokines such as IL-10 and TGF-β seems to be responsible of the persistent inflammation, the hallmark of clinical leishmaniasis." (PMID 31469834, 2019). "Lymphocytes (dermal CD4+ T cells) have been shown to be the main source of IL-10 in the Leishmaniasis-infected murine skin." (PMID 30072966, 2018). "During leishmaniasis, IL-10 plays an important role in suppressing the immune response and maintaining parasite persistence." (PMID 29352310, 2018). "In this context, the authors suggest that the IL-17 pathway is an important therapeutic target for the treatment of severe leishmaniasis in patients in whom IL-10 regulatory function is compromised." (PMID 29163510, 2017).
leishmaniasis (continued). "The cytokines IL-10 and TGF-β have been involved in homeostatic mechanisms of leishmaniasis by limiting the tissue damage caused by excessive inflammation." (PMID 26752985, 2016). "In leishmaniasis, phagocytes are stimulated to produce IL-10, which leads to a reduced production of cytokines related to the Th1 profile, such as IL-12 and interferon gamma (IFN-γ)." (PMID 26538837, 2015). "The importance of IL-10 in modulating the cytolytic activity of CD8+ T cells in human leishmaniasis is unclear." (PMID 26495321, 2015). "A role for IL-10 regulation of IL-17 is supported by studies in leishmaniasis, where blockade of IL-10 resulted in increased IL-17 and exacerbation of skin pathology." (PMID 25730203, 2015). "Recently, the balance between pro-inflammatory IFN-γ/TNF-α and regulatory IL-10 cytokines has been shown to be involved in the outcome of human leishmaniasis and in the prediction of vaccine success." (PMID 24786587, 2014). "Emerging evidence has associated increased lymphoid expression of the immunosuppressive IL-10 and TGF-β cytokines as underlying factors responsible for parasite persistence and chronicity in leishmaniasis." (PMID 24763747, 2014). "A successful vaccine against Leishmaniasis is still elusive despite several recent encouraging reports and success of such vaccine depends on the IL-10 production by Treg cells." (PMID 25032977, 2014). "We further show that DC-based vaccination against leishmaniasis suppresses the early secretion of IL-10 following challenge infection." (PMID 23825956, 2013). "This is perhaps not surprising, since a recent study from our laboratory found that rSSP4 induces a population of IL-10/IFN-γ CD4+ double producers T cells, which have also been identified as a major source of IL-10 during infections such as leishmaniasis." (PMID 23509755, 2013). "To develop a model to study Th1 associated pathology in leishmaniasis, we infected C57BL/6 mice in the ear with L. major, while simultaneously inhibiting IL-10 effects with anti-IL-10 receptor mAb." (PMID 23555256, 2013). "The finding that the early antigen-specific secretion of IL-10 by T cells influences the progression and outcome of leishmaniasis has clinically relevant implications." (PMID 23825956, 2013). "We further show that dendritic cell-based vaccination against leishmaniasis suppresses the early secretion of IL-10 following challenge infection." (PMID 23825956, 2013). "IL-10 secreted by Tregs are involved in persistence of parasites, regulation of Th2 cell expansion, and control of cell-mediated lesion development in leishmaniasis." (PMID 23060880, 2012). "As most of the studies evaluating the role of IL-10 in leishmaniasis are related to its indirect effects in T cells function, this subject will be discussed later in the section of adaptative immune response." (PMID 23060880, 2012). "In leishmaniasis a large variety of cells contribute to the production of IL-10, including DCs and macrophages." (PMID 23060880, 2012). "Herein, we demonstrated that the overall effect of Phlebotomus papatasi saliva was dominated by the activation of IL-10-producing CD8+ cells suggesting a possible detrimental effect of pre-exposure to saliva on human leishmaniasis outcome." (PMID 21991402, 2011). "IL-10 expression by Th1 cells has been reported to regulate the immune response in leishmaniasis and toxoplasmosis." (PMID 19646904, 2009). "Moreover, in previous studies, IP-10, and IFN-γ levels proved useful in monitoring the cellular immune response following treatment for active disease and IFN-γ, TNF-α, IL-10 and IL-2 indicated exposure to leishmaniasis." (PMID 40142579, 2025). "IL-10 is also an important regulatory cytokine in the immune response to human leishmaniasis." (PMID 38064516, 2023). "Hence, the aim of the present study was to perform a systematic review and meta-analysis to determine if IL-10 SNPs influence the progression of leishmaniasis." (PMID 35778471, 2022).